PKD2 (polycystin 2, transient receptor potential cation channel)
Diseases named in the same sentence as PKD2 in open-access papers (continued):
Sharing a sentence is not in itself a finding about the gene and the disease.
endothelial dysfunction (1 paper, 2025). In vascular diseases, endothelial dysfunction is a systemic pathological state of the endothelium (the inner lining of blood vessels) and can be broadly defined as an imbalance between vasodilating and vasoconstricting substances produced by (or acting on) the endothelium. "Recently endothelium-specific mutations in Pkd1 and Pkd2 were shown to independently cause endothelial dysfunction in mice." (PMID 40722835, 2025).
Glucose intolerance (1 paper, 2021). Glucose intolerance (GI) can be defined as dysglycemia that comprises both prediabetes and diabetes. "Of note, mice deficient for PKD2 enzymatic activity were protected from diet‐induced glucose intolerance and displayed better insulin sensitivity when fed HFD." (PMID 33949105, 2021).
Hepatitis (1 paper, 2018). Inflammation of the liver. "For lncRNAs dysregulated by hepatitis, lnc-PKD2-2:2 and lnc-RP11-650K20.3.1-2:1 expressions correlated with patient survival." (PMID 29416609, 2018).
Impaired glucose tolerance (1 paper, 2020). An abnormal resistance to glucose, i.e., a reduction in the ability to maintain glucose levels in the blood stream within normal limits following oral or intravenous administration of glucose. "Mutation of the PKD2 gene that encodes TRPP1 causes autosomal dominant polycystic kidney disease, but not diabetes or impaired glucose tolerance." (PMID 32168890, 2020).
invasive breast carcinoma (1 paper, 2009). A carcinoma that infiltrates the breast parenchyma. "We further show that decreased expression of PKD1 can serve as a marker for invasive breast cancer, whereas PKD2 and PKD3 expression remain unchanged in normal breast and invasive breast tumour tissue." (PMID 19243594, 2009).
liver fibrosis (1 paper, 2021). "Ask1 inhibition reduces kidney and liver fibrosis Cdc42 and Rac1 mediate JNK activation in the context of polycystin overexpression in cells and activate Mlk2 and Mlk3 However, in our model, Ask1 deletion or double deletion of Mlk2 and Mlk3 did not reduce cystic burden in Pkd2 mutants." (PMID 34962918, 2021).
lymph-node metastasis (1 paper, 2024). "PKD2 status did not correlate with sex (p = 0.07), smoking (p = 0.76), alcohol consumption (p = 0.61), tumor size (p = 0.47), lymph-node metastasis (p = 0.26), distant metastasis (p = 0.12), HPV infection (p = 1.00) or PKD3 status (p = 0.61)." (PMID 39408603, 2024).
mitral valve prolapse (1 paper, 2025). A fairly common and often benign valvular heart disorder characterized by redundancy or hooding of mitral valve leaflets so that they prolapse into the left atrium, often causing mitral regurgitation. "Among the 87 genotyped patients, a significant association was found between mitral valve prolapse and PKD1 truncating mutations (pairwise Fisher’s exact test PKD1 truncating versus PKD2 adjusted P-value = .007)." (PMID 41195291, 2025). "Among the 20 patients with mitral valve prolapse, 13 (65%) had PKD1 truncating mutations, 5 (25%) had PKD1 non-truncating mutations and 2 (10%) had PKD2 mutations." (PMID 41195291, 2025).
myeloma (1 paper, 2011). "However, in contrast to myeloma cells, incubation of undifferentiated C2C12 cells with different concentrations of IGF-1 did not result in activation of PKD2 (data not shown)." (PMID 21298052, 2011).
optic pathway glioma (1 paper, 2020). Optic pathway glioma (OPG) is a benign tumor that develop along the optic nerve (chiasm, tracts, and radiations) characterized by impairment or loss of vision and may be accompanied by diencephalic symptoms such as reduced growth and alteration in sleeping patterns. "In summary, this is the first reported case of concurrence of a truncated NF1 mutation with optic pathway gliomas and a nonsense PKD2 mutation." (PMID 32533764, 2020). "Conclusión: this is the first reported case of concurrence of a truncated NF1 mutation with optic pathway gliomas and a nonsense PKD2 mutation." (PMID 32533764, 2020).
oral squamous cell carcinomas (1 paper, 2022). "Cisplatin-activated autophagy promotes the expression of circ-PKD2, which plays a role as a tumor suppressor gene in the proliferation, migration, and invasion in oral squamous cell carcinoma (OSCC)." (PMID 35220397, 2022).
osteoporosis (1 paper, 2022). A condition of reduced bone mass, with decreased cortical thickness and a decrease in the number and size of the trabeculae of cancellous bone (but normal chemical composition), resulting in increased fracture incidence. "Primary cilia containing PKD2/PC2 and PKD1/PC1 operate as osteoporosis-related mechanoreceptors in osteoblasts and renal epithelial cells, and BICC1 has been found in renal cell primary cilia." (PMID 35756494, 2022).
Paralysis (1 paper, 2015). Paralysis of voluntary muscles means loss of contraction due to interruption of one or more motor pathways from the brain to the muscle fibers. "Notably, in contrast to pkd2 knockdown, the baseline ICOs observed at the bud stage are unaffected by ciliary paralysis, even though the normal increase in left-sided oscillations coinciding with ciliary motility is lost." (PMID 25660539, 2015).
pericardial effusion (1 paper, 2022). Fluid collection within the pericardial sac, usually due to inflammation. "Among two subjects who had both PKD1 and PKD2 mutations, one had pericardial effusion > 5 mm." (PMID 35207400, 2022). "Pericardial effusion was observed in subjects with PKD1 and PKD2 mutations." (PMID 35207400, 2022).
Polyhydramnios (1 paper, 2010). The presence of excess amniotic fluid in the uterus during pregnancy. "Selective inactivation of Pkd1 and Pkd2 in endothelial cells resulted in polyhydramnios and abnormalities similar to those observed in Pkd1−/− placentas." (PMID 20862291, 2010).
rectum adenocarcinoma (1 paper, 2025). An adenocarcinoma arising from the rectum. "Finally, in the rectum adenocarcinoma (READ) protein-protein interaction network, the number of nodes were 118, the number of edges was 109 (cutoff: 0.78), and the gene interacting with PRKD1 was PKD2." (PMID 40984898, 2025).
renal carcinoma (1 paper, 2010). A carcinoma arising from the epithelium of the renal parenchyma or the renal pelvis. "Because PKD2 and PKCν/PKD3 are not expressed in the cell lines tested, our results lead to the assumption that PKCμ is involved in the regulation of adhesion of the renal cancer cells CCF-RC1 and CCF-RC2." (PMID 20459627, 2010).
thoracic aortic aneurysm (1 paper, 2025). An aneurysm formed in the wall of the proximal portion of the descending aorta proceeding from the arch of the aorta. "Using the ClinGen framework, genes predisposing to heritable thoracic aortic aneurysms and dissection have been identified, though PKD1 and PKD2 mutations are considered risk alleles with limited evidence as a Mendelian cause of heritable thoracic aortic aneurysm and dissection." (PMID 40093803, 2025).
thyroid papillary carcinoma (1 paper, 2021). "Expression of mRNA encoding polycystin-2 (PKD2), a major ciliary Ca2+ channel in thyroid follicular cells, was lower in thyroid papillary carcinoma cells with LOF of primary cilia than in those with primary cilia." (PMID 33602982, 2021).
kidney disease (61 papers, 2008 to 2026). "ADPKD is the prevailing inherited renal disorder resulting from mutations in PKD1 (encoding polycystin-1) or PKD2 (encoding polycystin-2), which mainly presents with cysts of varying sizes in the kidneys bilaterally." (PMID 39975561, 2025). "Mutations in the PKD1 gene account for approximately 78-85% of patients and cause more severe forms of nephropathy than mutations in the PKD2 gene do." (PMID 41181723, 2025). "The TRPP2 channel is also named polycystin-2 (PC-2) and is encoded by the polycystic kidney disease 2 (PKD2) gene." (PMID 36145607, 2022). "Patients with PKD1 mutations present with more aggressive kidney disease than those with PKD2 mutations, so renal replacement therapy is performed at a younger age in patients with PKD1 gene mutations." (PMID 36422264, 2022). "For example, mutations in PKD1 are more prevalent and lead to more severe kidney disease when compared with PKD2 mutations." (PMID 33869988, 2021). "These include polycystic kidney disease-associated proteins (Pkd1, Pkd2), calcium/calmodulin-dependent protein kinases (Camk genes), and Regucalcin, but not randomly selected genes." (PMID 32457326, 2020). "Polycystic kidney disease 1 (Pkd1) and Pkd2 genes encoding for polycystin-1 (PC-1) and polycystin-2 (PC-2) form a mechanosensory complex in the primary cilia of kidney and vascular endothelial cells." (PMID 29057897, 2017). "Further, considerable renal disease variability has been observed among individuals with the same PKD2 mutations." (PMID 26753721, 2016). "The age of onset of renal disease progression in ADPKD has been observed 15 years earlier in patients from PKD1-linked families than patients from PKD2-linked families." (PMID 26753721, 2016). "Amo is ahomolog of the human transient receptor potential channel TRPP2, encoded by thePolycystic Kidney Disease 2 gene (PKD2)." (PMID 21625494, 2011). "While the PKD1 and PKD2 mutations are prevalent across all ethnic groups, there are some genetic variants more common in African American populations that may influence kidney disease progression." (PMID 39457385, 2024). "However, the penetrance of kidney disease is known to vary according to a specific gene (e.g., PKD2 vs. PKD1) or a specific mutation type (e.g., missense vs. truncating variants)." (PMID 38097619, 2023). "There is a clear genetic basis for ADPKD, a heterogeneous disorder resulting from gene mutations in the polycystic kidney disease 1 gene (PKD1) or polycystic kidney disease 2 gene (PKD2)." (PMID 41181723, 2025). "ADPKD is the most common monogenic kidney disease and an important cause of end-stage kidney disease, caused by mutations in the PKD1 or PKD2 genes in the majority of the cases, leading to dysfunction of their encoded proteins, PC-1 and PC-2." (PMID 40980664, 2025). "Far upstream element–binding protein 1 (FUBP1) binds to the 3′UTR of polycystic kidney disease 2 (PKD2) mRNA to inhibit PKD2 translation." (PMID 38625739, 2024). "With an estimated incidence of 1:1000 to 1:400 individuals, ADPKD is the most common single-gene inherited kidney disease primarily caused by pathogenic mutations in PKD1 and PKD2 genes, encoding polycystin-1 and polycystin-2, respectively." (PMID 37667185, 2023). "ADPKD is the most common hereditary kidney disease, resulting from mutations in PKD1 (MIM#: 601313) and PKD2 (MIM#: 173910) genes, located in chromosomes 16p13.3 (in approximately 85% of cases) and 4q22.1 (in approximately 15% of cases), respectively." (PMID 32533764, 2020). "The Polycystin-2 (Polycystic kidney disease 2 gene, PKD2) is involved in enamel–dentine signalling and tissue organisation, while ABCG2 (ATP-binding cassette sub-family G member 2) may help eliminate harmful substances during mineralisation." (PMID 40869999, 2025). "Nontruncating PKD2 mutations, associated with milder kidney disease, are linked to less responsive cilia compared to truncating PKD2 or PKD1 mutations." (PMID 38473800, 2024).
kidney disease (continued). "Our results suggest that genetic modifiers that affect the onset of this renal disease may be present in some families, such as the co-inheritance of a weak allele of PKD1 or PKD2 or a variant in a cis position concerning the major variant." (PMID 38541974, 2024). "Polycystic-kidney-disease 1 and PKD2 play essential roles in maintaining vascular wall integrity, suggesting that pathogenic variants in these genes could increase the risk of vascular-related events." (PMID 39063956, 2024). "ADPKD is the most common inherited renal disease, which is caused by mutations of PKD1 (encoding polycystin-1) or PKD2 (encoding polycystin-2) and is characterized by multiple cysts in the kidneys which enlarge over time and lead to end-stage renal disease failure." (PMID 35050181, 2022). "In contrast, the PKD2 nontruncating mutations that are associated with the mildest kidney disease would not exhibit the exaggerated sensitivity to Wnt inhibition." (PMID 33869988, 2021). "Using a nearby genetically interacting deficiency, we have found that the polycystic kidney disease 2 gene, pkd2, which encodes a member of the TRPP channel family, is also required for phagocytosis of apoptotic cells, thereby demonstrating a novel role for PKD2 in this process." (PMID 22347485, 2012). "Five genes (PKD1, PKD2, and COL4A3/A4/A5) accounted for the majority of diagnoses in both our cohort and others, suggesting that focusing on these common genes can capture most hereditary kidney disease cases." (PMID 40533884, 2026). "Interestingly, despite this moderate-sized cohort and a potential selection bias toward increased severity in PKD2, we were able to demonstrate significant prognostic value of PKD genotyping for renal disease prediction." (PMID 32398770, 2020).
tumor (45 papers, 2014 to 2026). "Only high PKD2 levels were statistically linked to elevated tumor grades, more advanced TNM tumor stages, and p16INK4a expression, while elevated PKD3 levels were associated with favorable disease-specific survival." (PMID 39408603, 2024). "High expression of PKD2 was strongly associated with poor tumor grade: 40% of grade 2 samples and 33% of grade 3 samples belonged to the high PKD2 category, while most of grade 1 samples showed low PKD2 protein levels." (PMID 39408603, 2024). "PKD2 has been associated with multiple types of cancer, functioning by promoting tumor progression and blocking type I IFN signaling." (PMID 32630675, 2020). "Furthermore, tumor lnc-PKD2-2-3 was negatively related to miR-328 but positively linked with GPAM in CCA (both P <0.05); meanwhile, tumor miR-328 negatively related to GPAM in CCA (P <0.01)." (PMID 35965521, 2022). "High PKD2 levels were linked with elevated tumor grades and more advanced TNM tumor stages, while elevated PKD3 levels were correlated with better patient outcomes." (PMID 39408603, 2024). "In many tumor types, PKD2 mediates EMT, tumor cell migration, and invasion in cooperation with PKD3, which has also been confirmed to participate in HNSCC tumor cell migration." (PMID 39408603, 2024). "The ARHGAP18 gene is involved in endothelial cell regulation and tumor angiogenesis, while the PKD2 protein which contains six transmembrane domains, plays a key role in autophagy, which is an intracellular degradation process under stressful stimuli." (PMID 39001376, 2024). "In vivo experiments further revealed that lnc-PKD2-2-3 overexpression promoted tumor volume and weight but repressed tumor apoptosis in xenograft mice; meanwhile, it increased GPAM expression but decreased miR-328 expression (all P <0.05)." (PMID 35965521, 2022). "Tumor lnc-PKD2-2-3 positively correlated with poor differentiation and N stage (both P <0.05), but did not relate to other clinicopathological features in CCA patients." (PMID 35965521, 2022). "TUNEL staining showed tumor apoptosis was reduced by lnc-PKD2-2-3 overexpression (P <0.05), but was enhanced by lnc-PKD2-2-3 knockdown (P <0.01)." (PMID 35965521, 2022). "Consistent with in vitro observations, circ-PKD2 overexpression significantly increased the chemosensitivity evident as reduced tumor volume and weight." (PMID 35220397, 2022). "Then it was observed that lnc-PKD2-2-3 overexpression promoted tumor volume and weight but repressed tumor apoptosis in xenograft mice; meanwhile, it increased GPAM expression but decreased miR-328 expression." (PMID 35965521, 2022). "In vivo experiments revealed that lnc-PKD2-2-3 overexpression increased tumor volume and weight (both P <0.05), whereas lnc-PKD2-2-3 knockdown decreased tumor volume and weight (both P <0.01) in xenograft mice." (PMID 35965521, 2022). "PKD2 protects tumor cells from apoptotic cell death by activating NF-κB signaling in several cancers." (PMID 33807058, 2021). "Regarding CRC, CIB1 induces tumor progression by promoting higher levels of vascular endothelial growth factor (VEGF) via Protein kinase D2 (PKD2) and thus is directly involved in angiogenesis." (PMID 34794407, 2021). "Much more evidences supported that PKD2/3 promoted inflammation and tumor procession in carcinoma and its microenvironments by regulating different cytokine expression and secretion." (PMID 30841931, 2019). "In xenograft mouse models, silencing PKD2 in MDA‐MB‐231 using shRNA led to significant reduction of tumor volume." (PMID 30652415, 2019). "In contrast, transcript levels of PKD2 and PKD3 showed the opposite trend, i.e. increased PKD2 or PKD3 expression in tumor vs. normal tissue." (PMID 30419840, 2018). "Specifically, for PKD2, the numbers of patient paired samples that showed increased, reduced or unchanged PKD2 expression in tumor vs. normal tissues were 7, 2 and 1, and for PKD3, the numbers were 6, 2 and 2, respectively." (PMID 30419840, 2018).